HSPB1P1 (heat shock protein family B (small) member 1 pseudogene 1)
Synonyms: formerly HSPBL2
Gene: Processed pseudogene on chromosome 9 (72,007,881 to 72,008,136, reverse strand). Ensembl gene ENSG00000236060.
Diseases named in the same sentence as HSPB1P1 in open-access papers:
HSPB1P1 is named in the same sentence as 3 diseases in open-access papers, as found by Europe PMC text mining. Sharing a sentence is not in itself a finding about the gene and the disease. The quoted sentences say what the papers report.
glioma (2 papers, 2020 to 2022). A benign or malignant brain and spinal cord tumor that arises from glial cells (astrocytes, oligodendrocytes, ependymal cells). "Pseudogenes PKMP3, AC027612.4, HILS1, RP5-1132H15.3 and HSPB1P1 were identified as prognostic predictors for lower-grade gliomas." (PMID 33378744, 2020).
HSPB1P1 also shares sentences with these, for which no sentence is quoted: breast carcinoma (1 paper); tumor (1).